MIF (macrophage migration inhibitory factor)
Diseases named in the same sentence as MIF in open-access papers (continued):
Sharing a sentence is not in itself a finding about the gene and the disease.
atherosclerosis (continued). "The HMG-Box Transcription Factor 1 (HBP-1) gene is a known target for miR-19a which leads to an increase in macrophage migration inhibiting factor (MIF) that links miR-19a overexpression to both acute coronary syndrome and atherosclerosis." (PMID 36071532, 2022). "The released MIF can promote the transformation of macrophages into foam cells and accelerate the progression of atherosclerosis." (PMID 36186991, 2022). "MIF is a critical mediator in the pathogenesis of various inflammatory and immune diseases such as septic shock, rheumatoid arthritis, and atherosclerosis, as well as several cancers." (PMID 35087852, 2021). "This atypical receptor can additionally bind CXCL11 and MIF, and studies have recently revealed its conflicting roles in atherosclerosis." (PMID 34501271, 2021). "Strikingly, MIF also has an important role in VSMCs and is thus involved in the advancement of atherosclerosis." (PMID 34501271, 2021). "The experiment constitutes a ‘proof-of-concept’ for such compounds in an in vivo disease setting and is a good predictor for their efficacy in advanced atherosclerosis models, but also other models involving MIF-related chronic inflammation." (PMID 33239628, 2020). "Inhibition of either the TF, thrombin‐mediated PAR‐1 signaling or MIF secretion prevented atherosclerosis in mice fed either a high‐fat diet (HFD) or a regular chow‐based diet." (PMID 32611229, 2020). "Macrophage migration inhibitory factor (MIF) has been recognized as a major player in the pathogenesis of atherosclerosis." (PMID 31924846, 2020). "Macrophage migration-inhibitory factor (MIF) is an atypical chemokine that promotes atherosclerosis through CXC-motif chemokine receptor-4 (CXCR4)." (PMID 33239628, 2020). "Two important chemokines associated with atherosclerosis are stromal cell-derived factor 1 (SDF1, also known as CXC1L12) and macrophage migration inhibitory factor (MIF)." (PMID 32664664, 2020). "The functional effect of the interactions between MIF and monocytes and T cells has been shown in mice with advanced atherosclerosis, where MIF-blockade led to decreased plaque infiltration by monocytes and T cells, together with a regression in plaque size." (PMID 31244846, 2019). "Macrophage migration inhibitory factor (MIF), a pleiotropic protein with inflammatory chemokine activity, is involved in chronic inflammatory processes, such as atherosclerosis." (PMID 30983881, 2019). "MIF plays an important role in pathophysiological processes such as atherosclerosis, diabetes, unstable plaque formation, and stress reaction." (PMID 30983881, 2019). "MIF has beendemonstrated to primarily promote atherosclerosis through the enhancement ofmacrophage and T cell recruitment by directly affecting endothelial-monocyteinteractions." (PMID 30506423, 2019). "Proinflammatory actions of MIF have been reported in various inflammatory diseases such as sepsis, rheumatoid arthritis, and atherosclerosis." (PMID 30057807, 2018). "Macrophage migration inhibitory factor (MIF) has been recognized as a key factor in the vascular processes leading to atherosclerosis." (PMID 29482504, 2018). "In fact, endothelial chemokine receptor CXCR4 activation at low shear stress can play a role in the development of atherosclerosis acting as an important mediator of the endothelial response to damage through interaction with MIF." (PMID 30356351, 2018). "MIF is a well-established mediator of a number of acute and chronic inflammatory diseases including atherosclerosis, chronic kidney disease, organ fibrosis, and rheumatoid arthritis." (PMID 29728137, 2018). "High MIF expression found in leukocytes which facilitates the initiation and progression of atherosclerosis." (PMID 29403061, 2018). "We uncovered that endothelial MIF is a novel shear stress sensitive cytokine, thus adding a new perspective of its role in relation to early development of atherosclerosis." (PMID 29403061, 2018).
atherosclerosis (continued). "The physiopathological process of ACS is the atherosclerosis where MIF operates as a major regulator of inflammation." (PMID 30057807, 2018). "Recent research showed that MIF increased monocyte recruitment during the process of atherosclerosis development." (PMID 29482504, 2018). "For example, in atherosclerosis, MIF activates CXCR2 and CXCR4, playing a major role in regulating inflammatory cell recruitment." (PMID 29120365, 2017). "MIF exerts predominantly pro-inflammatory effects in acute and chronic inflammation, as found in acute kidney or lung injury, sepsis, colitis, or atherosclerosis." (PMID 29120365, 2017). "As monocyte adhesion to the endothelium is a crucial step in the early stages of atherosclerosis, MIF is considered to be involved in the pathogenesis of atherosclerosis and is closely related to plaque stability." (PMID 28348463, 2017). "Macrophage migration inhibitory factor (MIF)—a key regulator in chronic and acute inflammation—also plays a role in the pathogenesis of atherosclerosis and is upregulated in monocytes and endothelial cells in human atherosclerotic lesions." (PMID 28018358, 2016). "It has been shown that MIF expression in atherosclerosis-related cells, like ECs, SMCs, monocytes, and T cells, positively correlates with atherosclerosis progression, implicating MIF in atherogenesis." (PMID 26175090, 2015). "In human, MIF was shown to be expressed in different stages of human atherosclerosis, markedly upregulated in vulnerable atheromatous plaques, and was associated with the weakening of the fibrous cap." (PMID 25821795, 2015). "Combined, all these studies clearly identify MIF and its receptors as an important mediator of leukocyte recruitment and atherosclerosis development." (PMID 26257740, 2015). "Recent years, CXCL12 and macrophage migration inhibitory factor (MIF) have gained a lot of interest in the field of atherosclerosis research." (PMID 26175090, 2015). "Macrophages migration inhibitory factor (MIF), as a pleiotropic cytokine, plays a critical role in several inflammatory conditions including various tumours, atherosclerosis, diabetes and obesity in both animal and human 7–11." (PMID 25661015, 2015). "The receptor for MIF, CXCR2, has also been implicated in atherosclerosis as CXCR2 deficiency results in reduced lesion size and lesional macrophage content." (PMID 26175090, 2015). "It was shown that upon hyperlipidemia, MIF expression is greatly enhanced in cells crucial for atherosclerosis development, like ECs, SMCs, monocytes, and T cells." (PMID 26257740, 2015). "MIF later emerged as an innate mediator of chronic inflammatory diseases such as atherosclerosis and arthritis." (PMID 24887129, 2014). "Blockade of MIF in Apoe−/− mice on high-fat diet resulted in the formation of smaller atherosclerotic lesions displaying a reduced macrophage and T-cell content, supporting a role for MIF in T-cell chemotaxis also in the context of atherosclerosis." (PMID 24966838, 2014). "This suggests potential different roles of CXCR4 and its ligand CXCL12 in atherosclerosis through interplay of CXCR4 with MIF." (PMID 24966838, 2014). "The proinflammatory cytokine macrophage migration inhibitory factor (MIF) is a major mediator of atherosclerosis." (PMID 25114912, 2014). "The macrophage migration inhibitory factor (MIF) is related to the progression of atherosclerosis, which, in turn, is a key factor in the development of acute coronary syndrome (ACS)." (PMID 25105152, 2014). "Recently, studies have been conducted on the roles of MIF in various inflammatory diseases, such as rheumatoid arthritis and atherosclerosis." (PMID 24167613, 2013). "A growing body of literature suggests that MIF is involved in pathomechanisms of sepsis, inflammatory and autoimmune diseases and atherosclerosis." (PMID 22693633, 2012).
atherosclerosis (continued). "Cyclooxygenase (COX)‐2 and MIF are indicators of inflammatory processes and regulate development and progression of atherosclerosis." (PMID 23316317, 2012). "Macrophage migration inhibitory factor (MIF) is involved in the progress of atherosclerosis and plaque destabilization and plays a pivotal role in the development of acute coronary syndromes (ACS)." (PMID 22693633, 2012). "Macrophage migration inhibitory factor (MIF) is a well known proinflammatory factor, and recent evidence suggests an important role of MIF in the progression of atherosclerosis and restenosis." (PMID 20727156, 2010). "Recently, macrophage migration inhibitory factor (MIF) has emerged as a key factor in vascular remodeling and in the development and progression of atherosclerosis." (PMID 20727156, 2010). "MIF exerts diverse biological functions, and altered expression has been reported in several inflammatory and metabolic disorders, including rheumatoid arthritis, atherosclerosis, and diabetes." (PMID 41036138, 2025). "It has also been suggested that Gremlin1 may act as an inhibitor of macrophage migration inhibitory factor (MIF) in atherosclerosis." (PMID 38250154, 2024). "Combined with present and previous studies, we uncovered the involvement of HOTAIR in atherosclerosis, at least in part, we demonstrate that HOTAIR alleviates the formation of foam cell and inflammatory reaction by inhibiting miR-19a-3p in atherosclerosis through TNF-α/miR-19a/HBP1/MIF pathway." (PMID 38250607, 2024). "MIF is involvement in the preclinical atherosclerosis process based on low-grade inflammation, has pro-inflammatory and pro-atherogenesis functions, and has become the main regulator of atherosclerosis." (PMID 36824264, 2023). "Clinical studies have confirmed a close relationship between MIF and atherosclerosis (AS), during which MIF can accelerate AS through immune reaction, inflammation, and oxidative stress, and promote neuronal death after stroke, and thus aggravate the development of stroke." (PMID 36824264, 2023). "MIF could accelerate atherosclerosis (AS) through immune reaction, inflammation, and oxidative stress, and promote neuronal death, and thus aggravate the development of stroke." (PMID 37190581, 2023). "The heterocomplex impacts on thrombus size and platelet morphology implying that CXCL4L1 could have a protective role in atherosclerosis by mitigating the pro-atherosclerotic effects of MIF via complex formation." (PMID 36094626, 2022). "Macrophage migration inhibitory factor (MIF) is a potent pro-inflammatory cytokine that mediates the inflammatory process in atherosclerosis, and the variation of the MIF gene may be related to the occurrence of CAD." (PMID 35733129, 2022). "MIF promotes carcinogenesis and plays a central role in atherosclerosis pathogenesis." (PMID 35115654, 2022). "MIF could potentially promote the development of a myeloproliferative syndrome while it may accelerate atherosclerosis development." (PMID 35115654, 2022). "When atherosclerotic plaques occur, serum MIF levels increase rapidly, suggesting that MIF may be involved in the occurrence of atherosclerosis." (PMID 36186991, 2022). "In contrast, monocyte-function appeared to remain mainly stable in the presence of TET2 mutations, with the exception of the promotion of macrophage migration inhibitory factor (MIF), a pivotal factor for monocytic differentiation, that is characteristically elevated in atherosclerosis." (PMID 36355225, 2022). "The interactions between Gremlin-1 and MIF may also be important in regulation of monocyte function and survival in atherosclerosis." (PMID 35091838, 2022).
atherosclerosis (continued). "Inhibition of MIF-mediated T-cell migration by CXCL4L1 complexation could potentially be relevant in atherosclerosis, where it might represent a feedback mechanism that could serve to dampen the atherogenic response." (PMID 36094626, 2022). "The role of MIF in atherosclerosis has been intensively investigated." (PMID 36712241, 2022). "In addition to its role in inflammation, MIF had been linked to OSA, and cardiovascular diseases such as atherosclerosis, myocardial infarction, coronary heart diseases and hypertrophy." (PMID 36142186, 2022). "The role of MIF in the progress of atherosclerosis has drawn intensive attention." (PMID 35046995, 2021). "Furthermore, antibody inhibition and genetic deletionstudies have revealed that MIF influences the promotion of atherosclerosis byenhancing macrophage and T cell recruitment." (PMID 30506423, 2019). "Although advances haverecently been made in understanding how P.gingivalis promotes atherosclerosis, a detailedunderstanding of how the activities of MIF and its functional receptors participatein atherosclerotic diseases remains unclear." (PMID 30506423, 2019). "Suppressing MIF expression with an inhibitor or neutralizing antibody in individuals with manifest atherosclerosis may be a potential therapeutic intervention for treating this condition." (PMID 29482504, 2018). "We show that endothelial cell-specific MIF can be up-regulated by pro-atherogenic OS, but down-regulated by LS which is intrinsically athero-protective, suggesting a potential early role in the process of atherosclerosis." (PMID 29403061, 2018). "Our findings identified a clue for the role of MIF in P. gingivalis-promoted atherosclerosis." (PMID 29482504, 2018). "MIF is a proinflammatory cytokine that plays a critical role in the initiation and progression of chronic inflammatory and immune-mediated diseases such as atherosclerosis." (PMID 29482504, 2018). "For example, MIF promotes atherosclerosis by activating proinflammatory atherogenic pathways." (PMID 29120365, 2017). "Moreover, intercellular cell adhesion molecule-1(ICAM-1), chemoattractant protein-1(MCP-1), and macrophage migration inhibitory factor (MIF), which regulate the adhesion of monocytes, are dysregulated in hyperglycemia-induced atherosclerosis in animal models." (PMID 28883907, 2017). "The human (Homo sapiens) chemokine-like protein macrophage migration inhibitory factor (HsMIF) is a pivotal mediator of inflammatory, infectious and immune diseases including septic shock, colitis, malaria, rheumatoid arthritis, and atherosclerosis, as well as tumorigenesis." (PMID 25888527, 2015). "Increased MIF plasma levels promote vascular inflammation and development of atherosclerosis." (PMID 26485680, 2015). "The profile of activities of MIF in vivo and in vitro is strongly suggestive of a role for MIF in the pathogenesis of many inflammatory diseases, including atherosclerosis, and hence antagonism of MIF is suggested as a potential therapeutic strategy in inflammatory disease." (PMID 25661015, 2015). "MIF is considered to play a critical role in the development of atherosclerosis." (PMID 25821795, 2015). "MIF regulates inflammatory cell activation and release of other pro-inflammatory cytokines and its pathological role has been reported in various inflammatory disorders, such as rheumatoid arthritis, atherosclerosis and cardiovascular diseases." (PMID 26359352, 2015). "Because MIF inhibition has been shown to induce the stabilization and even regression of atherosclerotic plaques, MIF represents a potential drug target for the treatment of atherosclerosis." (PMID 25821795, 2015). "Hence, our study has further demonstrated that MIF gene interference effectively inhibits atherosclerosis process and stabilizes vulnerable plaque in STZ-induced diabetic apoE−/− mice." (PMID 25661015, 2015). "Various functional animal studies confirmed the role of MIF in atherosclerosis development." (PMID 26257740, 2015).
atherosclerosis (continued). "Thus, MIF gene interference stabilizes atherosclerosis plaque likely by inhibiting MMP-2 and MMP-9 expression, up-regulating TIMP-1 expression and decreasing the ratio of MMP-2/TIMP-1." (PMID 25661015, 2015). "Several researches have focused on the role of MIF in the atherosclerosis process." (PMID 25105152, 2014). "This review discusses MIF’s role as a chemokine-like mediator, addressing its structure, receptor binding capacity and importance in leukocyte recruitment, particularly arrest, in the context of atherosclerosis." (PMID 23720662, 2013). "Because MIF can be readily measured in plasma and other tissue fluids in different disease states, the different roles of MIF as a biomarker in pathogenesis and progression of atherosclerosis are an important area of inquiry." (PMID 22577254, 2012). "Thus, many studies revealed MIF to be involved in the pathogenesis of inflammatory diseases, such as atherosclerosis, rheumatoid arthritis, sepsis, asthma, and acute respiratory distress syndrome." (PMID 22363104, 2012). "In the view of the increased expression of MIF in the atherosclerosis, we hypothesized that MIF might be up-regulated by hypoxia in VSMCs, and the up-regulation of MIF could be mediated via HIF-1 dependent pathway." (PMID 20727156, 2010). "In view of the important role of MIF and hypoxia to atherosclerosis, our findings might contribute to the understanding of the pathogenesis of progressive atherosclerosis." (PMID 20727156, 2010). "However, the regulation of MIF expression in vascular cells, and its mechanisms of action have received little attention in atherosclerosis research." (PMID 20727156, 2010). "Both MIF and hypoxia play critical roles in inflammation and atherosclerosis." (PMID 20727156, 2010). "Previous studies have found that MIF is involved in the preclinical atherosclerosis process based on low-grade inflammation, and is associated with hypoendothelial function and increased vascular stiffness, while arteriosclerosis may be a common pathogenesis of CSVD." (PMID 37190581, 2023). "This is in line with the notion that acute elevations of MIF serum levels may ameliorate ischemia-reperfusion injury after cardiac surgery, whereas long-term elevations in MIF may aggravate inflammatory pathways in atherosclerosis." (PMID 32932965, 2020). "The upregulation of SOD1, CAT, MIF, and PPARγ observed in this study is in line with previous works, which have demonstrated the antioxidant proprieties of a diet rich in nuts, related to the regulation of cellular pathways of atherosclerosis, inflammation, and oxidative stress." (PMID 31354906, 2019). "Interestingly, downregulation of KLF2 in ST conditions also lead to higher expression of the pro-inflammatory EC-specific MIF, consistent with KLF2 operating as a homeostatic modulator of MIF expression in endothelial cells, intrinsically protective against atherosclerosis." (PMID 29403061, 2018). "Thus, we hypothesized that EC-specific MIF, a pro-inflammatory cytokine, contributes to the process of atherosclerosis with its atherogenic effect naturally inhibited by LS in vivo." (PMID 29403061, 2018). "We hypothesized that P. gingivalis infection promotes the formation of atherosclerosis through MIF." (PMID 29482504, 2018). "MIF may activate macrophage and induce hemorrhagic microvessels in atherosclerosis." (PMID 25821795, 2015). "MIF may have a critical role in the pathogenesis of CHD, which is mainly caused by atherosclerosis." (PMID 25821795, 2015). "However, to date, the link between MIF and diabetes-associated atherosclerosis has not been established." (PMID 25661015, 2015). "Thus, MIF gene interference inhibits inflammation, which could chiefly attribute to its inhibiting of atherosclerosis process and stabilizing of atherosclerosis plaque." (PMID 25661015, 2015). "Besides, MIF may act beyond inflammatory cytokine, as suggested by its proliferative effect on vascular smooth muscle cells demonstrated in atherosclerosis." (PMID 22363104, 2012).